MALT1 (MALT1 paracaspase)
Diseases named in the same sentence as MALT1 in open-access papers (continued):
Sharing a sentence is not in itself a finding about the gene and the disease.
periodontitis (3 papers, 2021 to 2023). An acute or chronic inflammatory process that affects the tissues that surround and support the teeth. "Our group has demonstrated that levels of MCPIP-1 and MALT-1 are regulated by periodontitis-associated bacteria in monolayers of gingival keratinocytes." (PMID 37010640, 2023). "Another study found that the modified MCPIP-1 and MALT-1 response and protein expression induced by periodontitis-related bacteria may be part of the pathogenesis of periodontitis." (PMID 37198606, 2023). "In both healthy and periodontitis-affected human gingival tissues, MALT-1 was detectable at all layers of gingival epithelium being especially prominent at the layers of stratum basale, stratum spinosum, and stratum granulosum and less observed in stratum corneum." (PMID 37010640, 2023). "However, it is also worth considering the possibility of MALT-1 activation, especially in a long-term infection process, as periodontitis is, which would result in aggravated and prolonged MCPIP-1 depletion." (PMID 34182783, 2021). "Finally, smoking, which is a major risk factor for periodontitis, may influence the expressions of MCPIP-1 or MALT-1 through its effects on immune cell response or oral microbial colonization and thus must be taken into account in further studies." (PMID 37010640, 2023). "In the context of periodontitis, however, little is known about the expression profile of MCPIP-1 and MALT-1 in the gingival tissues in relation to the extension of infection and inflammation." (PMID 37010640, 2023). "Further studies should be conducted to elucidate the role of MCPIP-1/MALT-1 in periodontitis and determine whether targeting the crosstalk between immune response and MCPIP-1/MALT-1 has benefits in periodontal treatment." (PMID 37010640, 2023).
spinal cord ischemia (3 papers, 2023 to 2025). Reduced blood flow to the spinal cord which is supplied by the anterior spinal artery and the paired posterior spinal arteries. "MALT1 also exacerbates ischemic brain injury and spinal cord ischemia/reperfusion (SCI/R) injury by promoting glial endoplasmic reticulum stress, neuroinflammation, and neuronal damage, with its inhibition alleviating these effects." (PMID 41567547, 2025). "Another study revealed that blockage of MALT1 alleviates the endoplasmic reticulum of glia in spinal cord ischemia/reperfusion injury and downregulates M1 polarization of microglia in the spinal cord." (PMID 36960276, 2023).
T-cell acute lymphoblastic leukemia (3 papers, 2020 to 2022). Acute lymphoblastic leukemia of T-cell origin. "T-cell acute lymphoblastic leukemia is an aggressive malignancy that does not respond well to chemotherapy; according to one study, it is biologically dependent on the proteolytic activity of the mucosa-associated lymphoid tissue lymphoma translocation protein 1 (MALT1) protease." (PMID 33401649, 2021).
adult T cell leukemia (2 papers, 2022 to 2025). "Mutations of CARD11, which can be found in an aggressive subtype of DLBCL, Sézary syndrome, angioimmunoblastic T-cell lymphoma (AITL), and adult T-cell leukemia/lymphoma (ATLL), disrupt the auto-inhibition of CARD11 and drive its receptor-independent oligomerization, thus activating MALT1." (PMID 35203553, 2022).
Allergy (2 papers, 2018 to 2022). An allergy is an immune response or reaction to substances that are usually not harmful. "In our prior work, we showed that the MALT1 association with PA allergy risk is further reflected in higher total psIgE levels and the number of major allergenic components (Ara h 1, Ara h 2, and Ara h 3)." (PMID 34981778, 2022). "The highly specific relationship between Ara h 2 IgG4 and HLA DQA1*01:02 is in marked contrast to our findings with another allergy-related gene, MALT1, found to be associated with progression to PA in the LEAP avoiders." (PMID 34981778, 2022).
Ataxia (2 papers, 2019 to 2023). Ataxia refers to impaired coordination of voluntary muscle movement. "Recently, four independent papers reported unexpected autoimmune phenotypes such as multi-organ inflammation, including the stomach, and ataxia in full-body Malt1-PD mice, which could indicate a risk when inhibiting MALT1 protease activity for therapeutic reasons." (PMID 31474984, 2019). "Despite the difference in peripheral Treg number, both T cell-specific and full-body Malt1-PD mice develop ataxia and multi-organ inflammation to a similar extent." (PMID 31474984, 2019). "As previously observed, Malt1 PD-T mice showed hunched posture and developed ataxia." (PMID 36761777, 2023). "Therefore, we investigated the role of MALT1 proteolytic activity in thymic Treg development in young healthy (ataxia-free) Malt1-PD and -PDT mice." (PMID 31474984, 2019). "We could confirm this in cLN from young disease-free Malt1-PD mice and in mice already suffering from ataxia." (PMID 31474984, 2019). "Since the T cell-specific Malt1-PDT mice show as severe disease development as the full-body Malt1-PD mice, we can conclude that absence of MALT1 protease activity in T cells only is sufficient to induce ataxia and weight loss to a similar extent as induced by its absence in all body cells." (PMID 31474984, 2019). "Just like in the full-body Malt1-PD mice, the T cell-specific Malt1-PDT mice displayed a weight retardation, starting from approximately 9 weeks of age, and ataxia, starting on average at 11–12 weeks of age." (PMID 31474984, 2019). "To assess whether disease development in Malt1-PD and -PDT mice was due to the same mechanism, we evaluated cytokine production by CD44+ CD4+ T cells in cervical lymph nodes (cLN) of mice already suffering from ataxia." (PMID 31474984, 2019). "Notably, at the time of sacrifice, when the mice had developed ataxia, the number of peripheral Tregs in Malt1-PDT mice is higher than in Malt1-PD mice, indicating that also MALT1 protease-dependent signals from non-T cells may promote peripheral Treg induction." (PMID 31474984, 2019).
autoimmune encephalitis (2 papers, 2020 to 2025). Inflammation of the brain secondary to an immune response triggered by the body itself. "In MALT1 deficient mice, Th17 cells appeared to be non-pathogenic in the induction of experimental autoimmune encephalitis." (PMID 32870913, 2020).
colorectal cancer (2 papers, 2022 to 2023). A primary or metastatic malignant neoplasm that affects the colon or rectum. "The effect of MALT1 protease inhibition on colorectal cancer (CRC) cell proliferation and survival was analyzed in vitro using the cell lines Caco2, HT-29, and HCT116." (PMID 37108564, 2023).
cutaneous melanoma (2 papers, 2017 to 2021). A primary melanoma arising from atypical melanocytes in the skin. "Further analysis of the Cancer Genome Atlas showed that cutaneous melanoma cases with MALT1 gene mutation and mRNA overexpression were associated with a shortened median disease-free survival." (PMID 28759024, 2017).
enteropathy (2 papers, 2018 to 2022). "Homozygous MALT1 mutations result in a phenotype of primary antibody deficiency together with enteropathy and a reduction in Tregs." (PMID 29686669, 2018).
Failure to thrive (2 papers, 2018 to 2022). Failure to thrive (FTT) refers to a child whose physical growth is substantially below the norm. "MALT1 deficiency is characterized by recurrent sinopulmonary infections, enteropathy, eczema, periodontal disease, and failure to thrive." (PMID 30283440, 2018).
food allergies (2 papers, 2022 to 2023). "Genetic association studies have identified some risk alleles for food allergies, particularly in the genes MALT1, FLG, and HLA; these findings implicate genes involved in immune and barrier function in the development of food allergies." (PMID 36501184, 2022).
gastroenteritis (2 papers, 2017 to 2022). An inflammatory disorder that affects the upper and lower gastrointestinal tract. "The reason might be as follows: (a) MALT1 activated NF‐κB signaling pathway; meanwhile the activation of NF‐κB pathway was correlated with the secretion of various inflammatory cytokines (including IL‐1, IL‐6, TNF‐α, etc.)as well as the severity of intestinal inflammation." (PMID 34997981, 2022).
influenza (2 papers, 2017 to 2022). An acute viral infection of the respiratory tract, occurring in isolated cases, in epidemics, or in pandemics; it is caused by serologically different strains of viruses (influenzaviruses) designated A, B, and C, has a 3-day incubation period, and usually lasts for 3 to 10 days. "Our study revealed a novel role of MALT1 in regulating alveolar macrophage MMP-9 production and showed that MALT1 deficiency alleviates the severity of influenza." (PMID 29018444, 2017). "Taken together, we demonstrated a novel role of MALT1 in regulating alveolar macrophage MMP-9 production whose presence exacerbates the severity of influenza." (PMID 29018444, 2017). "MALT1 mediates the production of MMP-9 in alveolar macrophages, which is involved in influenza pathogenesis and exacerbates the severity of influenza." (PMID 35467421, 2022).
liver cancer (2 papers, 2016 to 2021). An epithelial or non-epithelial malignant neoplasm that arises from the liver. "We also found that MALT1 expression is upregulated in HepG2 and SK-Hep1 liver cancer cell lines versus LO2 normal liver cell line both in RNA and protein levels contrary to TIFA." (PMID 29263897, 2016). "MALT1 dysregulation together with another lncRNA, HULC (highly upregulated in liver cancer), promotes the growth of liver cancer stem cells." (PMID 34439391, 2021).
ovarian carcinoma (2 papers, 2020 to 2022). A malignant neoplasm originating from the surface ovarian epithelium. "We also identified the additional CTCFL targets ACTBL2, MALT1, and PCDH7 to be predictive for ovarian cancer treatment outcomes." (PMID 35132075, 2022).
rectal adenocarcinoma (2 papers, 2021 to 2023). "Most commonly gained or lost genes seen in rectal adenocarcinoma (FLT3, CDX2, GNAS, BCL2, SMAD4, MALT1) are not found in rectal squamous cell carcinoma." (PMID 36357817, 2023).
Stroke (2 papers, 2018 to 2021). Sudden impairment of blood flow to a part of the brain due to occlusion or rupture of an artery to the brain. "Besides, MALT1 positively correlated with the National Institutes of Health Stroke Scale score." (PMID 34273195, 2021).
allergic asthma (1 paper, 2018). A asthma with a basis in a pathological type I hypersensitivity reaction. "Evidence for a potential contribution of MALT1 to allergic asthma comes from two studies showing that CARMA1 is important in mouse models of allergic asthma." (PMID 30214442, 2018).
Arthritis (1 paper, 2022). Inflammation of a joint. "Oral administration of a MALT1 inhibitor reduced disease severity and synovial cytokine production in a rat collagen-induced arthritis model." (PMID 35615349, 2022). "Genetic inactivation or pharmacological inhibition of MALT1 protects against experimental autoimmune encephalomyelitis (EAE), arthritis, psoriasis, and colitis." (PMID 35615349, 2022).
asthma (1 paper, 2023). "MALT1 levels, on the other hand, have been shown to be higher in children with a higher frequency of asthma exacerbations and to correlate positively with T2 asthma but negatively with T2 low asthma." (PMID 38057814, 2023).
auto-inflammatory syndromes (1 paper, 2022). "However, development of MALT1 inhibitors to treat autoimmune and inflammatory diseases (A&ID) has been hindered by reports linking MALT1 inhibition and genetic loss-of-function to reductions in regulatory T-cell (Treg) numbers and development of auto-inflammatory syndromes." (PMID 35615349, 2022).
benign prostatic hyperplasia (1 paper, 2023). A non-cancerous nodular enlargement of the prostate gland. "Since studies have suggested a positive correlation between ARv7 expression and NF-κB activity in human benign prostatic hyperplasia and CRPC, we continued to study whether ARv7 was involved in the upregulation of MALT1-inducing NF-κB activity in androgen-independent prostate cells." (PMID 37047218, 2023).
breast invasive carcinoma (1 paper, 2021). "In PAAD, breast invasive carcinoma (BRCA), and COAD, MALT1 expression was positively correlated with that of most immune checkpoint genes." (PMID 34926571, 2021).
Cachexia (1 paper, 2017). Severe weight loss, wasting of muscle, loss of appetite, and general debility related to a chronic disease. "Animal growth and viability in homeostatic conditions are not affected by the absence of MALT1, yet, Malt1PM mice develop severe cachexia with increased numbers of T and B cells in the lymph nodes." (PMID 29018444, 2017).
Candida infections (1 paper, 2018). "In humans, the role for MALT1 in protecting against invasive Candida infections has been obscured by the major importance of MALT1 in T cells and B cells." (PMID 30446641, 2018).
cerebrovascular disease (1 paper, 2021). "However, no relevant clinical study explores the correlation of MALT1 with Th1 and Th17 cells in cerebrovascular disease patients such as AIS patients." (PMID 34273195, 2021).
cervical carcinoma (1 paper, 2023). A carcinoma arising from either the exocervical squamous epithelium or the endocervical glandular epithelium. "Several lncRNAs, including HOTAIR, H19, mucosa-associated lymphoid tissue 1 (i.e., MALT1), growth arrest-specific 5 (i.e., GAS5), cervical carcinoma high expressed 1 (i.e., CCHE1), and Pvt1 oncogene (i.e., PVT1), are crucial in tumorigenesis, invasion, metastasis, and radio-resistance." (PMID 37081411, 2023).
Cognitive impairment (1 paper, 2024). Abnormal cognition is characterized by deficits in thinking, reasoning, or remembering. "HECTD3 promotes NLRP3 inflammasome and pyroptosis, thereby exacerbating diabetes-related cognitive impairment by stabilizing MALT1 and regulating the JNK pathway." (PMID 38384936, 2024).
colon cancer (1 paper, 2017). "Furthermore, since regorafenib has already been approved by the U.S. FDA for the treatments of colon cancer and gastrointestinal stromal tumor utilization of this drug in treating MALT1-related cancers such as ABC-DLBCL should be easily adopted." (PMID 29371921, 2017).
depression (1 paper, 2018). "In contrast, ERA virus-inoculated MALT1−/− mice presented the first clinical signs at around 15 dpi and developed severe disease, characterized by limb paralysis and depression, requiring euthanasia at 17 or 18 dpi." (PMID 29367251, 2018). "In agreement with the curtailed immune response, MALT1−/− mice developed severe disease, characterized by severe depression and paralysis and requiring human euthanasia, whereas MALT1+/+ mice developed only mild disease resolving at 11 dpi, characterized by transiently reduced activity." (PMID 29367251, 2018).
diabetic retinopathy (1 paper, 2021). "Thus, inhibition of LncRNA MALT1 may become one of the therapeutic options for preventing the development and the progression of diabetic retinopathy." (PMID 35010703, 2021). "The results of a recent study indicated that LncRNA MALT1 facilitated its transcription by increasing the binding of the transcription factor at the Keap1 promoter, which results in preventing a translocation of the master regulator Nrf2 and losing the antioxidant defense in diabetic retinopathy." (PMID 35010703, 2021).
endothelial dysfunction (1 paper, 2021). In vascular diseases, endothelial dysfunction is a systemic pathological state of the endothelium (the inner lining of blood vessels) and can be broadly defined as an imbalance between vasodilating and vasoconstricting substances produced by (or acting on) the endothelium. "The possible reasons were as follows: (a) higher MALT1 expression could promote vascular inflammation and endothelial dysfunction, thereby leading to an unfavorable prognosis in AIS patients." (PMID 34273195, 2021). "Although MALT1 promotes vascular inflammation and induces endothelial dysfunction, no relevant study investigates its clinical application in AIS patients." (PMID 34273195, 2021).
Hyperkeratosis (1 paper, 2019). Hyperkeratosis is a histopathological term defining a thickened stratum corneum and may be present in many different skin conditions, with many possible overlaps. "The Malt1-KO mice suffer from erosive lesions in the neck and face region, with the epidermis showing acanthosis, hyperkeratosis, and parakeratotic scaling, as well as CD3+ T cell infiltration." (PMID 31632405, 2019).
ischemic stroke (1 paper, 2025). A stroke disorder caused by obstruction of blood flow to the brain, due to thrombotic (local blood clot formation) or embolic (due to a blood clot or other material traveling from another site) event. "In ischemic stroke, MALT1 regulates GluN2B phosphorylation and calcium overload through its interaction with HECTD4, with downregulation reducing neuronal damage." (PMID 41567547, 2025).
metastatic melanoma (1 paper, 2017). A melanoma that has spread from its primary site to another anatomic site. "Our studies demonstrate that MALT1 is increased in metastatic melanoma at the mRNA and protein levels." (PMID 28759024, 2017).
non-Hodgkin lymphoma (1 paper, 2023). Distinct from Hodgkin lymphoma both morphologically and biologically, non-Hodgkin lymphoma (NHL) is characterized by the absence of Reed-Sternberg cells, can occur at any age, and usually presents as a localized or generalized lymphadenopathy associated with fever and weight loss. "The first clinical trials using the MALT1 inhibitor JNJ-67856633 are currently ongoing in patients with non-Hodgkin’s Lymphoma and CLL (Clinical trials.gov; NCT03900598 and NCT04876092)." (PMID 36922488, 2023).
osteoporosis (1 paper, 2022). A condition of reduced bone mass, with decreased cortical thickness and a decrease in the number and size of the trabeculae of cancellous bone (but normal chemical composition), resulting in increased fracture incidence. "Regarding to the relationship between Malt1 and bone mass, as a matter of fact, the patient with Malt1 deficiency had growth inhibition and severe osteoporosis." (PMID 35927754, 2022). "Deletion of Malt1 in mouse T cells (Malt1TcellKO) protects against development of autoimmune arthritis but leads to spontaneous osteoporosis." (PMID 35927754, 2022).
primary effusion lymphoma (1 paper, 2018). A large B-cell lymphoma located in the body cavities, characterized by pleural, peritoneal, and pericardial fluid lymphomatous effusions and that is always associated with human herpes virus-8 (HHV-8). "Recently, we have uncovered a role for MALT1 protease activity in the development of primary effusion lymphoma (PEL)." (PMID 30214442, 2018).
pulmonary fibrosis (1 paper, 2023). Chronic progressive interstitial lung disorder characterized by the replacement of the lung tissue by connective tissue, leading to progressive dyspnea, respiratory failure, or right heart failure. "For instance, it has been reported that inhibition of MALT1 reduces tissue injury in pulmonary fibrosis model mice." (PMID 36960276, 2023).